MIR1258 (microRNA 1258)
Synonyms: hsa-mir-1258; MIRN1258; mir-1258
Gene: MicroRNA gene on chromosome 2 (179,860,836 to 179,860,908, reverse strand). Ensembl gene ENSG00000221240.
Homologues: Orthologues: chimpanzee ptr-mir-1258 (100% identical).